ZBP1 (Z-DNA binding protein 1)
Description:
Key innate sensor that recognizes and binds Z-RNA structures, which are produced by a number of viruses, such as herpesvirus, orthomyxovirus or flavivirus, and triggers different forms of cell death. ZBP1 acts as an essential mediator of pyroptosis, necroptosis and apoptosis (PANoptosis), an integral part of host defense against pathogens, by activating RIPK3, caspase-8 (CASP8), and the NLRP3 inflammasome (By similarity). Key activator of necroptosis, a programmed cell death process in response to death-inducing TNF family members, via its ability to bind Z-RNA: once activated upon Z-RNA-binding, ZBP1 interacts and stimulates RIPK3 kinase, which phosphorylates and activates MLKL, triggering execution of programmed necrosis (By similarity). In addition to TNF-induced necroptosis, necroptosis can also take place in the nucleus in response to orthomyxoviruses infection: ZBP1 recognizes and binds Z-RNA structures that are produced in infected nuclei by orthomyxoviruses, such as the influenza A virus (IAV), leading to ZBP1 activation, RIPK3 stimulation and subsequent MLKL phosphorylation, triggering disruption of the nuclear envelope and leakage of cellular DNA into the cytosol. ZBP1-dependent cell death in response to IAV infection promotes interleukin-1 alpha (IL1A) induction in an NLRP3-inflammasome-independent manner: IL1A expression is required for the optimal interleukin-1 beta (IL1B) production, and together, these cytokines promote infiltration of inflammatory neutrophils to the lung, leading to the formation of neutrophil extracellular traps (By similarity). In addition to its direct role in driving necroptosis via its ability to sense Z-RNAs, also involved in PANoptosis triggered in response to bacterial infection: component of the AIM2 PANoptosome complex, a multiprotein complex that triggers PANoptosis (By similarity). Also acts as the apical sensor of fungal infection responsible for activating PANoptosis (By similarity). Involved in CASP8-mediated cell death via its interaction with RIPK1 but independently of its ability to sense Z-RNAs (By similarity). In some cell types, also able to restrict viral replication by promoting cell death-independent responses (By similarity). In response to Zika virus infection in neurons, promotes a cell death-independent pathway that restricts viral replication: together with RIPK3, promotes a death-independent transcriptional program that modifies the cellular metabolism via up-regulation expression of the enzyme ACOD1/IRG1 and production of the metabolite itaconate (By similarity). Itaconate inhibits the activity of succinate dehydrogenase, generating a metabolic state in neurons that suppresses replication of viral genomes (By similarity). (Microbial infection) In case of herpes simplex virus 1/HHV-1 infection, forms hetero-amyloid structures with HHV-1 protein RIR1/ICP6 which may inhibit ZBP1-mediated necroptosis, thereby preventing host cell death pathway and allowing viral evasion.
Synonyms: DAI; C20orf183; DLM1; dJ718J7.3; DLM-1
Tractability: PROTAC: ubiquitination databases record sites on it.
Gene: Protein-coding gene on chromosome 20 (57,603,575 to 57,620,576, reverse strand). Ensembl gene ENSG00000124256.
Subcellular location: Cytoplasm; Nucleus; Cytoplasm (Isoform 7)
Pathways (Reactome):
Immune System: IRF3 mediated activation of type 1 IFN; RIP-mediated NFkB activation via ZBP1; Regulation of innate immune responses to cytosolic DNA; ZBP1(DAI) mediated induction of type I IFNs
Disease: Potential therapeutics for SARS
Gene Ontology:
Molecular function: DNA binding; protein binding; RNA binding; left-handed Z-DNA binding; double-stranded RNA adenosine deaminase activity
Biological process: antiviral innate immune response; defense response to virus; necroptotic signaling pathway; activation of innate immune response; defense response to fungus; positive regulation of apoptotic process; positive regulation of inflammatory response; positive regulation of necroptotic process; positive regulation of pyroptotic inflammatory response; positive regulation of type I interferon-mediated signaling pathway; regulation of inflammatory response; regulation of interleukin-1-mediated signaling pathway; immune system process
Cellular component: cytoplasm; cytosol; nucleus
Genetic constraint (gnomAD): Loss-of-function variants: 43 observed, 42.85 expected, observed/expected ratio (o/e) 1, 90% interval 0.79 to 1.29. The upper end of that interval is the gene's LOEUF score, 1.29, which puts it in group 5 of 6, group 1 being the genes least tolerant of losing a copy. Missense variants: 562 observed, 561.8 expected, observed/expected ratio (o/e) 1, 90% interval 0.93 to 1.07. Synonymous variants: 214 observed, 208.27 expected, observed/expected ratio (o/e) 1.03, 90% interval 0.92 to 1.15.
Homologues: Orthologues: chimpanzee ZBP1 (98% identical), macaque ZBP1 (87% identical), pig ZBP1 (53% identical), dog ZBP1 (52% identical), guinea pig ZBP1 (51% identical), mouse Zbp1 (45% identical), rat Zbp1 (45% identical).
Diseases named in the same sentence as ZBP1 in open-access papers:
ZBP1 is named in the same sentence as 135 diseases in open-access papers, as found by Europe PMC text mining. Sharing a sentence is not in itself a finding about the gene and the disease. The quoted sentences say what the papers report.
viral infection (100 papers, 2013 to 2026). "Z-DNA-binding protein 1 (ZBP1), encoded by Zbp1, induces inflammation and cell death in response to sensing Z-form nucleic acids that arise during viral infection." (PMID 40065807, 2025). "Next, we evaluated the gene expression of Z-DNA binding protein (ZBP1), implicated in cell death pathways upon viral infections." (PMID 39417078, 2024). "This aggregation was significantly reduced following the RHIM1 mutation, whereas the RHIM2 mutation had little effect on ZBP1 aggregation under viral infection conditions." (PMID 38982083, 2024). "This gene encodes Z-DNA-binding protein 1, identified as an innate sensor of viral infections that is induced by IFN with effects including regulation of cell death and inflammation." (PMID 37607995, 2023). "In the future, it will be interesting to look for loss-of-function of ZBP1 in genetically undefined cases of HSV-1 encephalitis or other viral infections." (PMID 37450010, 2023). "ZBP1 plays a crucial role in controlling virus replication, and deletion of ZBP1 is significantly associated with severe viral infections." (PMID 36263798, 2022). "ZBP1 is the master regulator of one of the induction pathways of necroptosis, which is mainly caused by virus infection." (PMID 36615244, 2022). "Although independent groups have linked ZBP1 function to necroptosis, they have reported opposing susceptibility phenotypes to viral infection with the previous ZBP1−/− mice." (PMID 33526566, 2021). "To test if binding of Z‐form nucleic acids to ZBP1 is involved in the induction of cell death during virus infection, we mutated key conserved residues involved in Z‐RNA/DNA binding in mouse ZBP1." (PMID 28716805, 2017). "Thus, it is commonly assumed that once ZBP1 binds Z-form nucleic acid ligands during viral infection, it directly associates with and activates RIPK3." (PMID 39345610, 2024). "We put forward the hypothesis that loss of IFIH1 and ZBP1 provided an evolutionary advantage by reducing inflammation-induced damage to host tissues and thereby contributed to a switch from resistance to tolerance of viral infections in pangolins." (PMID 32574256, 2020). "Z-DNA Binding Protein 1 (ZBP1) is a critical pattern recognition receptor within the innate immune response to viral infection." (PMID 42079158, 2026). "Most evidence linking ZBP1 to PANoptosome assembly in response to viral infection comes from murine bone-marrow-derived macrophages, with only limited parallel data available from human systems." (PMID 41440542, 2025). "Upon viral infection—particularly with coxsackievirus B3 (CVB3)—cytosolic viral sensors such as Z-DNA-binding protein 1 (ZBP1) and RIG-I are upregulated in cardiomyocytes." (PMID 40832143, 2025). "These pro-PANoptotic effects of impaired autophagy have been primarily demonstrated in murine viral infection models, particularly influenza-induced ZBP1 activation, with human data being more indirect." (PMID 41440542, 2025). "Numerous illnesses and ailments, such as viral infections and autoimmune disorders, have been connected to ZBP1." (PMID 41299204, 2025). "Z-DNA/Z-RNA has been implicated in innate immune sensing, particularly through interactions with Z-DNA binding protein 1 (ZBP1), which can trigger necroptosis in response to viral infection." (PMID 41020605, 2025). "While full activation of the PANoptotic cascade is rare under physiological conditions, type I interferons or viral infections (e.g., lymphocytic choriomeningitis virus) can induce ZBP1 expression in T cells, sensitizing them to PANoptosis." (PMID 41440542, 2025). "For instance, autophagy has been shown to promote ZBP1-dependent PANoptosis during viral infection, and autophagy-mediated degradation of c-FLIP or other anti-apoptotic factors can enhance caspase-8 activation, lowering the threshold for PANoptosis initiation." (PMID 41440542, 2025).
viral infection (continued). "ZBP1 is known to initiate RIPK3-mediated necroptosis in murine models of viral infection, but how this pathway is regulated in human cells is unclear." (PMID 39982916, 2025). "Z-DNA binding protein 1 (Zbp1) is a sensor for aberrant nucleic acids — such as noncoding RNA, misfolded RNA/DNA structures, or viral nucleic acids, including those derived from viral infections such as influenza A virus and cytomegalovirus." (PMID 40359032, 2025). "Recently, it has been found that sensing of Z-NA (including Z-RNA and Z-DNA) by ZBP1 has essential roles in pathogenesis of virus infection or other inflammatory conditions." (PMID 41488643, 2025). "The PANoptosis activator ZBP1 is induced in innate immune cells -particularly macrophages and dendritic cells- in response to viral infection or interferon signaling, promoting PANoptosome assembly and activation." (PMID 41440542, 2025). "ZBP1 is a key cell death gene that detects intracellular double-stranded RNA or Z-form nucleic acids during viral infection and induces necroptosis and apoptosis." (PMID 41465783, 2025). "Recently, ZBPs were also identified to be encoded in the genomes of several giant viruses, and another recent study suggests that ZBP1 forms condensates with liquid–liquid phase separation properties upon viral infection." (PMID 41020605, 2025). "In viral infections, the detection of cytosolic viral nucleic acids by sensors such as ZBP1 or AIM2 can result in the robust assembly of PANoptosomes and the demise of inflammatory cells." (PMID 40422233, 2025). "In severe neutrophilic asthma, insults like viral infection can activate ZBP1, forming a ZBP1-based PANoptosome." (PMID 41394843, 2025). "Through a combination of RNA sequencing and genetic studies, we demonstrate that PRV VP22 functions as a virus-encoded virulence factor by evading the inhibitory effects of ZBP1 on virus infection." (PMID 39475237, 2024). "Some reports have shown that ZBP1 regulates the inflammatory response in viral infection, which is consistent with our results." (PMID 38822277, 2024). "Studies have found that ZBP1 acts as an innate sensor for virus infection and triggers multiple programmed cell death pathways including apoptosis, necroptosis, and pyroptosis." (PMID 39614405, 2024). "Z-DNA binding protein 1 (ZBP1) functions as a pivotal innate immune sensor that regulates inflammatory cell death during viral infections." (PMID 39475237, 2024). "Emerging evidence suggests that ZBP1 activates the NLRP3 inflammasome during certain viral infections, leading to IL-1β production and inflammation (23, –, 25)." (PMID 39475237, 2024). "Sensing the virus-derived Z-nucleic acid (Z-NA) is critical for ZBP1 to activate necroptosis during virus infection." (PMID 38952452, 2024). "Recently, ZBP1 has been shown to recognize Z-RNA as the ligand to trigger RIPK3-mediated necroptosis during virus infection." (PMID 39345610, 2024). "Whereas interferon beta 1 (IFNB1)-based antiviral therapies are generally effective to treat viral infections, ZBP1-triggered inflammatory cell death limits the therapeutic efficacy of IFNB1 during coronavirus infection." (PMID 38932258, 2024). "Recent studies have highlighted ZBP1’s involvement in mediating cellular death responses to diverse stress signals, including viral infections and inflammatory stimuli." (PMID 39465383, 2024). "Recent studies have identified Z-DNA binding protein 1 (ZBP1) as an innate sensor of viral infections and endogenous nucleic acid ligands such as mitochondrial DNA (mtDNA), regulating cell death, inflammasome activation, and inflammatory responses." (PMID 39026271, 2024). "The expression of ZBP1 is upregulated in most cases of viral infections (e.g., IAV, HIV-1, HSV-1, and ZIKA)." (PMID 38932258, 2024). "Upon viral infection, ZBP1 acts as an upstream sensor, assembling the ZBP1-PANoptosome with proteins such as RIPK3 and caspase-8, leading to lung injury in infections like IAV." (PMID 39676169, 2024).
viral infection (continued). "Expression of OASL1–mCherry effectively sequestered both RIPK3 and ZBP1 into its condensate in the cytoplasm during virus infection." (PMID 36604592, 2023). "Impairment of ADAR1 function or severe viral infection can lead to the excessive accumulation of Z-RNA, which trigger an exaggerated necrosis pathway mediated by ZBP1." (PMID 37771585, 2023). "Viral RNAs are ZBP1 agonists upon virus infection, although yet-to-be-defined cellular RNAs also contribute to ZBP1 activation in this setting." (PMID 37450010, 2023). "Z-DNA-binding protein 1 (Zbp1) can be induced by type I interferons (IFNs) to upregulate IFN expression after viral infection, thus activating the expression of interferon regulatory factor 1 (IRF1)." (PMID 36851724, 2023). "Once bound to the Z-DNA structure, ZBP1 influences the cells in tumor tissues, tricking the immune system into perceiving a viral infection, thus destroying the tumor tissue." (PMID 37569878, 2023). "Recognition of Z-DNA/RNA by ZBP1 promotes host resistance to viral infection but can also drive detrimental autoinflammation." (PMID 37450010, 2023). "ZBP1 thereby plays important roles in many disease settings, ranging from viral infection and inflammation to cancer, and efforts to target ZBP1 are underway." (PMID 37450010, 2023). "Of these ISGs, ZBP1 has been reported to trigger inflammatory cell death in several contexts, including viral infection with IAV." (PMID 35587515, 2022). "The nucleic acid sensor ZBP1 is emerging as a promiscuous regulator of cell death in response to virus infection." (PMID 36040212, 2022). "Recent studies have also reported that ZBP1 induces necroptosis in non-viral infections and mediates necrotic signal transduction by a unique mechanism." (PMID 36615244, 2022). "One critical ISG that plays a role in cell death during other viral infections is ZBP1, and its complex roles in innate immunity and inflammatory cell death have recently been discovered." (PMID 35587515, 2022). "The cellular ZBP1 protein is a known cytosolic sensor of DNA and its expression is induced as one of the ISGs during viral infection." (PMID 35203445, 2022). "In the future, the role of ZBP1 in different virus infections needs to be explored to determine the genome sequence that produces Z-NA." (PMID 36615244, 2022). "While previous research has mainly focused on the role of ZBP1 in restricting viral infection, more recent investigations have demonstrated that ZBP1 is also involved in heatstroke, skin inflammation, antitumor immunity and bacterial invasion." (PMID 36539813, 2022). "PANoptosis was reported to be activated by Z-DNA-binding protein 1 (ZBP1) in the context of viral infection with the influenza A virus (IAV)." (PMID 35847583, 2022). "In terms of necroptosis, early studies focused on viral infection, which demonstrated that ZBP1, as a receptor of viral RNA (vRNA), triggered cell death pathways predominantly via necroptosis and inflammatory response." (PMID 36615244, 2022). "ZBP1 has emerged as a crucial viral Z-RNA sensor to regulate cell death and inflammation during viral infections." (PMID 35587190, 2022). "Analysis of the classical role of ZBP1 in viral infection is also related to its original role as a viral sensor." (PMID 36615244, 2022). "Here, ZBP1 acted as an innate sensor of IAV recognizing Z-RNA in the viral ribonucleoprotein (vRNP) complex to induce necroptosis to resist virus infection." (PMID 36615244, 2022). "ZBP1 was found to mediate the interferon-induced necroptosis pathway in response to viral infection." (PMID 33526566, 2021). "ZBP1 (Z-binding protein 1), also known as DAI (DNA-dependent activator of IFN regulatory factors) or DLM1, was initially recognized as a sensor for double-stranded DNA (dsDNA) but later found its role as an RNA sensor during virus infections (55, –, 58)." (PMID 34372694, 2021).